MMP9 (matrix metallopeptidase 9)
Diseases named in the same sentence as MMP9 in open-access papers (continued):
Sharing a sentence is not in itself a finding about the gene and the disease.
tumor (continued). "At the same time, TAMs and tumour cells can promote angiogenesis by releasing enzymes to generate angiogenesis, such as MMP2, MMP‐7, MMP‐9, MMP‐12 and cyclooxygenase‐2 (COX‐2) to improve the invasiveness and motility of cells." (PMID 35961680, 2023). "Our previous work has shown that a spheroid mixture of BMSCs and HNC tumor cells induces osteogenic markers, such as alkaline phosphatase (ALP) and Runx2, and differentially expresses and secretes MMP-9, resulting in increased cell invasion." (PMID 37833873, 2023). "Specifically, during tumor initiation, neutrophils can produce reactive oxygen species (ROS), matrix metalloprotein (MMP9), and reactive nitrogen species (RNS), which further promote tumor initiation." (PMID 35692190, 2023). "EMT promotes tumor metastasis by upregulating or downregulating the expression of epithelial markers such as MMP-2, MMP-9, VEGF, vimentin, E-cad, and N-cad." (PMID 37020791, 2023). "All enrolled patients were on bone-targeting agents at study entry, and it has been shown in vitro that bone-targeting agents (including clodronate, pamidronate and zoledronic acid) can inhibit tumor cell expression of MMP2 and MMP9." (PMID 36765529, 2023). "Nevertheless, higher expressions of some factors were observed by stromal cancer-associated fibroblasts compared with fibroblasts from previous biopsy (MMP-9 and TIMP-3) or to fibroblasts from non-tumor zones of prostatectomy (MMP-2 and TIMP-3)." (PMID 37108185, 2023). "Intraperitoneally injected Plasmodium has been shown to reduce MMP9 production by inhibiting IGF-1 signaling through the accumulation of hemozoin, thus inhibiting tumor angiogenesis in vivo." (PMID 38274735, 2023). "Additionally, the suppression of the matrix metalloproteinase-2 (MMP-2) and MMP-9 expression by Luteolin is another mechanism that has been shown to be related to the anticancer effects of Luteolin on colon cancer by inhibiting angiogenesis, a crucial factor for tumor progression." (PMID 36992138, 2023). "The growth of solid tumours depends on the formation of new blood vessels (angiogenesis), affecting the size of the tumour and the process of metastasis, which are closely related to the levels of VEGF, MMP-2, and MMP-9." (PMID 37446252, 2023). "Tumor tissue analysis revealed significant levels of MMP-2 and MMP-9 expression and their active forms." (PMID 38069361, 2023). "MMP-9 release of the inactive domains allowed assembly of active anti-CD3 VH and VL domains on the surface of tumor cells." (PMID 36793863, 2023). "Among the MMP family, MMP-2 and MMP-9 are documented as substrate-specific gelatinases that are pivotal in ECM degradation and are advantageous for invasion and metastasis of tumor cells, leading to tumorigenesis." (PMID 37964204, 2023). "This study will evaluate tumor metastasis biomarkers (VEGF-A, MMP-3, MMP-9), inflammatory factors, immune function and clinical outcomes." (PMID 36910600, 2023). "Areas of MMP-9 and MMP-2 positive staining were also detectable in the tumor cells and fibroblast-like cells." (PMID 37175975, 2023). "In the orthotopic TNBC mouse model, the cRGD-lipo-LGAL-treated group showed reduced tumor growth and lung metastasis, accompanied by suppressing TAK1 activation and MMP9 expression, compared to those in the cRGD-lipo control group." (PMID 37041137, 2023). "In order to determine the potential therapeutic efficacy of inhibiting MMP-9 function in cancer therapy, it is necessary to develop specific inhibitors of MMP-9, to inhibit the tumour promoting function of MMP-9 instead of suppressing the anti-tumour effect." (PMID 36765669, 2023). "MMP-9 activation enhances the chemotaxis and migration of LSCC tumor cells to cervical lymph nodes which is mediated by chemokine receptor 7 (CCR7)." (PMID 37600570, 2023). "At the same time, MMP2 and MMP9, and other MMPs can be regulated by activated AKT, and tumor cells with excessive activation of the PI3K/AKT signaling axis are more likely to undergo EMT." (PMID 37686118, 2023).
tumor (continued). "Meanwhile, in both HCT116 and HT29 colon tumor cells treated with [64Cu]CuCl2 an important fingerprint of hypoxia was registered through the upregulation of HMOX1, MMP9, and SERPINE1." (PMID 37415761, 2023). "In contrast, ASPA knockdown resulted in increased tumor weights and up-regulated expression of PCNA, cyclin D1, N-cadherin, and MMP9 (P < 0.05 or P < 0.01), concomitant with the inhibition of E-cadherin expression (P < 0.01)." (PMID 37271807, 2023). "MMP2 is a Zn2+-dependent proteolytic enzyme that hydrolyzes type IV collagen, activates MMP9 to degrade ECM, helps tumor cells break through the basement membrane, and plays a very important role in tumor migration and invasion." (PMID 37174639, 2023). "Matrix metalloproteinase 9 (MMP-9), an integral part of NETs, degrades extracellular matrix and supports tumor metastasis." (PMID 37958788, 2023). "It increases endothelial cell proliferation and migration, tumour growth in vivo, and remodels the perivascular matrix by increasing levels of proteinases, including matrix metalloproteinases MMP2 and MMP9." (PMID 37446252, 2023). "In A431 tumor cells, TGM2 activates PI3K/Akt signaling pathway that results in the upregulation of MMP-9 and an increase in cell adhesion, migration, invasion, and cancer metastasis." (PMID 36831225, 2023). "CUR is a multitarget drug capable of decreasing the expression of molecules involved in angiogenesis, such as VEGF, and tumor invasion, such as intracellular adhesion molecule-1 (ICAM-1), MMP-2, and MMP-9 in CCA." (PMID 37371856, 2023). "Recent studies have shown that when cocultured with GC cells, M2-polarised macrophages secrete MMP9 via upregulated COX-2 expression, promoting tumour angiogenesis and invasion of GC." (PMID 38143746, 2023). "Previously we evaluated that plasma and serum MMP-9, its tissue inhibitor TIMP-1 and classical tumor marker (CEA) levels were significantly higher in GC patients compared with healthy controls." (PMID 37240178, 2023). "The following aspects were compared: clinical efficacy, serum tumor markers, serum VEGF and MMP-9 contents, inflammatory factors, incidence of adverse reactions, limb function scores at 6 months of follow-up, and prognostic quality of life (QOL)." (PMID 36880008, 2023). "Overexpression of S100A4 led to increased tumor cell invasion, metastasis, and angiogenesis and downregulation of S100A4 reduced VEGF and MMP9 expression." (PMID 37853467, 2023). "Some network pharmacological studies have shown that the anti-tumor-related targets of H. diffusa are closely related to MAPK-8, STAT3, and MMP9." (PMID 36188592, 2022). "Numerous studies demonstrated that MIF has been involved in the migration and invasion of cancer cells by up-regulating the pro-metastatic mediators MMPs, among which MMP2 and MMP9 degrades the ECM and facilitates the tumor cell invasion and metastasis." (PMID 36703790, 2022). "TIMP-2 regulates MMP-9 and MMP2 expression at the protein and mRNA levels and prevents further metastasis of tumor cells." (PMID 35770085, 2022). "We assessed the expression levels of candidate invasion-specific protein biomarkers CTSK, MMP9, MMP2, TIMP2, and PTTG1 by immunohistochemical staining in paraffin-embedded NFPA tumor tissues." (PMID 36052250, 2022). "It is involved in tumor invasion and progression and can activate other MMPs, such as MMP-1, MMP-7, MMP-8, MMP-9 and MMP-13, which have an established role in OSCC." (PMID 36547091, 2022). "MMP9 is part of the gelatinase family that breakdowns the ECM proteins gelatin and type IV collagen, thereby promoting tumour invasion and metastasis." (PMID 36263033, 2022). "Neutrophils are the primary source of metalloproteinase-9 (MMP-9), which promotes the release of vascular epithelial growth factor (VEGF) to create the tumor vasculature." (PMID 36387183, 2022).
tumor (continued). "The results of this study showed that these compounds are potentially effective blockers of tumor cell migration and metastasis, by inhibiting MMP-2 and MMP-9 expression and activation through regulation of the MAPK signaling pathway." (PMID 35269801, 2022). "MDSCs promote tumor angiogenesis through up-regulating VEGF, matrix metallopeptidase 9 (MMP9) and bombina variegata peptide 8 (Bv8)." (PMID 35154134, 2022). "Together, these findings oppose a crucial role of MMP-9 and MMP-2 in the observed combined effects of CXCL12 and CXCL11 on tumor cell invasion." (PMID 36539774, 2022). "MMP-9 also facilitates the release of tissue‐bound fibroblast growth factor (FGF) and vascular endothelial growth factor (VEGF), thus contributing to tumor growth." (PMID 36242015, 2022). "Among genes significantly downregulated by MEG3 knockdown, as determined by a −2 fold-change from MEG3-knockdown to control, were MMP-1, MMP-9, and MMP-16, three metalloproteases with previously characterized roles in tumor metastasis." (PMID 36231143, 2022). "Fuling in other studies has been shown to influence multiple intracellular pathways in different cancer types, including downregulation of MMP-9, TGF-β and upregulation of tumor suppressor genes." (PMID 36727068, 2022). "Pro-angiogenic factors that are released by neutrophils, such as VEGF, Bv8, MMP-9, and S100A8/S100A9, directly induce tumor angiogenesis via the activation of endothelial cell proliferation." (PMID 35158807, 2022). "The growth factors also stimulate cancer cells to produce and secrete TFG-β, MMP9 and MMP13 which contribute to the proliferation and angiogenesis of the tumor." (PMID 36226048, 2022). "The 12 downregulated genes were functionally involved in 8 pathways, including tumor maker (TP63, MMP9, and EGR3 genes) and antigen processing (HLA-F-AS1 and HLA-A genes)." (PMID 35915657, 2022). "F. nucleatum can also trigger the production of matrix metalloproteinase-9 (MMP-9) and MMP-12, which are important factors for the tumor proliferation, invasion and metastasis in epithelial cells." (PMID 36059542, 2022). "As evidenced by IHC staining, the expression levels of KIF20A, MMP-2, MMP-9 and MKI67 increased significantly in tumor tissues in the KDELR2 overexpression group." (PMID 36096734, 2022). "MDSCs can also regulate tumor angiogenesis and remodel the microenvironment through VEGF, bFGF, Bv8, and MMP-9 to promote tumor progression." (PMID 36237303, 2022). "Meanwhile, Mmp3, Mmp9, Mmp16 and Mmp10, which belong to the MMP family and are closely related to tumor metastasis, were downregulated." (PMID 35296801, 2022). "We also observed a significant increase in the expression levels of VEGF and MMP-9, confirming increased angiogenesis in OPM-BMG tumor xenografts." (PMID 36591481, 2022). "Remodeling of the ECM allows for the migration of tumor cells, but also endothelial cells, e.g., via the activity of matrix metallopeptidase 2 (MMP2) and matrix metallopeptidase 9 (MMP9)." (PMID 36231134, 2022). "The expression of MMP-9 was also found to decrease after FAM107A overexpression, suggesting that FAM107A overexpression reduces tumor aggressiveness." (PMID 36010909, 2022). "CAIX overexpression increases MMP9 expression and FAK and steroid receptor coactivator (Src) phosphorylation, promoting tumor cell motility in oral squamous cell carcinoma." (PMID 36497411, 2022). "Silencing CD44 and FN1 in EO771 cells and MDA-MB-231 cells downregulated MTT-based viability as well as the expression of Lrp5, MMP9, Runx2, and Snail in EO771 cells, whereas their silencing significantly suppressed MSN-induced tumor inhibition." (PMID 34976221, 2022). "Erlotinib suppressed the TGF-β1–induced EMT phenotype in A549 cells and inhibited the MMP-9 levels in the LLC1 cells and LLC1 tumor-bearing mice." (PMID 36547898, 2022).
tumor (continued). "ING5 suppresses proliferation, migration, invasion and tumor growth of various cancer cells via the suppression of EGFR/PI3K/Akt, IL-6/STAT3, Akt/NF-κB/NF-κB/MMP-9 or IL-6/CXCL12 pathway." (PMID 36425530, 2022). "Several studies showed that the MMP-9 level is positively correlated with a higher tumor grade in BC tissue, and TPA mediated tumor invasion and migration by upregulating expression of MMP-1 and MMP-9 in BC cells." (PMID 36119505, 2022). "MHC class IIlow TAM increases the production of IL-10 and TGF-β to inhibit T cell proliferation and the secretion of MMP-9 and VEGF to promote tumor metastasis." (PMID 35163097, 2022). "MMPs, in particular MMP-2, MMP-9 and MMP-14,57 facilitate tissue remodelling, a vital process during neo-angiogenesis and tumour progression." (PMID 33758004, 2022). "The tumor tissues examined the impacts of circTRIM28 knockdown and tamoxifen treatment on circTRIM28, miR-409-3p, HMGA2, PCNA, Cleaved-caspase 3, and MMP9 expression." (PMID 36180890, 2022). "Previous studies demonstrated that STAT3 can directly or indirectly interact with the promoters of cyclin D1, Twist, MMP2, MMP7, MMP9, VEGF, upregulate their expression and regulate cell proliferation, tumor metastasis and angiogenesis." (PMID 36295083, 2022). "In vivo assays showed that tumor with higher expression of POU2F1 had stronger staining of ki67 and produced more MMP9." (PMID 35562740, 2022). "MMP-2 and MMP-9 are more critical for angiogenesis than for ECM degradation, which are considered to be the key to promoting tumor angiogenesis." (PMID 36065269, 2022). "Overall, differential analysis revealed that LCN2 and MMP9 were widely upregulated in several tumor types, while an opposite trend was observed for SLC22A17, suggesting its potential role in tumor suppression." (PMID 36211450, 2022). "For instance, a recent report demonstrated that MMP-9, when derived from macrophages, is essential for EMT in tumor cells via activation of protease-activated receptor (PAR-1,)." (PMID 35216088, 2022). "Collectively, our findings establish LPAL2 as a novel tumor suppressor in HCC, and suggest targeting LPAL2 and MMP9 as a therapeutic approach for the treatment of HCC." (PMID 36010685, 2022). "On this basis, CD160, MMP-9, PTGDS, SLC26A8, and TLR5 were selected as indicators of tumor detection." (PMID 36733384, 2022). "To elucidate the mechanism of the anti-tumor action of Hsp90ab1 and MSN, we evaluated their downstream protumorigenic genes such as TGFβ, Runx2, Snail, and MMP9, as well as PDL1 24 that inhibits immune responses and KDM3A 25 that regulates histone methylation." (PMID 34976221, 2022). "APOA1 also regulates inflammation signals through the STAT3 signaling pathway and reduces matrix metalloproteinase-9 (MMP-9) levels, which is an important factor that promotes tumor proliferation and metastasis." (PMID 35421932, 2022). "Because component changes in ECM induce EMT, MMP2 and MMP9 can also induce and promote EMT to promote tumour progression." (PMID 36408277, 2022). "NF-κB has a significant promoting effect on tumor metastasis, and it can promote the expression of tumor metastasis-related genes VCAM-1, MMP-9, etc.." (PMID 35378772, 2022). "In BCC's stroma and the peritumoral area, CAFs can secrete an array of MMPs (e.g., MMP-1, MMP-2, MMP-3, MMP-9, MMP-11, MMP-13, MMP-14, MMP-19), all of them promoting ECM remodeling and favoring tumor escape from the anti-tumoral action of the immune cells." (PMID 35572966, 2022). "Interestingly, expression analysis of MDA-byb1 and -hyb2 tumor hybrids revealed appropriate upregulation of EMT-associated genes, such as SLUG, collagen, fibronectin, N-cadherin, MMP3, and MMP9, possibly indicating that tumor hybrids might have acquired a mixed E/M state." (PMID 35562905, 2022).
tumor (continued). "The expression levels of N-cadherin, Vimentin, Snail, MMP9 and HIF-1α were significantly decreased in the xenograft tumor tissues from mouse model injected with M2 cells treated with OL, when compared with those of the control group." (PMID 36050634, 2022). "A variety of MMPs, including MMP-2, MMP-9 and MMP-14, can degrade the basal layer of capillaries and promote exosmosis of tumor cells." (PMID 36776395, 2022). "The VM contributes to tumor proliferation and invasion in many types of cancers through the upregulation of several proteins, including matrix metalloproteinase (MMP)-2, MMP-9, vascular endothelial growth factor (VEGF), and growth factor-β1 (TGF-β1)." (PMID 35747793, 2022). "MMP-9 can cleave many extracellular matrix (ECM) proteins and regulate ECM remodelling, which can be used as a marker of tumour invasion and metastasis, and its expression level is positively correlated with tumour invasion and metastasis." (PMID 35264209, 2022). "In PC, BRCA1 co-regulates the AR activity mediating tumor progression, while BRCA2 limits the metastatic potential of PC by MMP9 downregulation and inhibition of the PI3K/AKT and MAP/ERK pathways (which also regulate PD-L1 expression)." (PMID 35203446, 2022). "From all MMPs, MMP-9 showed elevated expression and is considered an essential factor in HCC being a promoter of tumor metastasis and angiogenesis as well." (PMID 35081125, 2022). "The protein family of matrix metalloproteinases can degrade extracellular matrix components, whose well-known role is modulating tumor metastases, such as MMP2, MMP9, MMP7, MMP13, and MMP14." (PMID 35690612, 2022). "Western blot was applied to measure the mitigation of Mcl-1, PCNA, MMP-2, MMP-9, biomarkers of EMT process and the activation of caspase cascade, reflecting the influence of ID09 to tumor malignant biological behaviors in vivo." (PMID 35002504, 2022). "These signaling molecules have been reported to promote the production of MMP-9 from tumor cells, leading to the degradation of the ECM and the subsequent adhesion of disseminated tumor cells." (PMID 35805039, 2022). "Tumor sections from sericite-fed mice exhibited less neovascularization (CD31, brown) and a lower metastatic index (MMP-9, brown) than those from the saline group." (PMID 36199546, 2022). "Neutrophils have been shown to support tumor angiogenesis via the release of numerous pro-angiogenic factors, such as VEGF, FGF-2, oncostatin M, IL-17, MMP-9, Bv8, S100A8/9 alarmins, STAT3, and NETs." (PMID 35158807, 2022). "Studies have shown that MMP9 and CXCL8 can be biomarkers to predict prognosis and indicate a more aggressive phenotype of tumor." (PMID 35321506, 2022). "In tumor spheroids co‐cultured with TIMP‐1‐silenced hASCs, the activities of MMP‐1 and MMP‐9 were significantly higher than those in the control." (PMID 35600659, 2022). "Following the pattern observed in heparanase and MMP9 levels, vimentin showed a tendency to decrease in stage III when compared to stage II in tumor tissue." (PMID 36139645, 2022). "Studies have verified that the PI3K/AKT signaling pathway participates in tumor angiogenesis by regulating several pro-angiogenic cytokines, such as VEGFA and MMP9." (PMID 35436935, 2022). "This evidence was corroborated by the opposite trend observed in the LGG tumor showing downregulation of LCN2 and MMP9 along with hypermethylation of the promoter region." (PMID 36211450, 2022). "The resulting PP2A activity, which inhibits the PI3K/AKT/NF‐κB pathway, led to the inhibition of tumour invasion and metastasis via decreasing the expression of MMP2, MMP9, and Snail in MDA‐MB‐231 cells." (PMID 35811356, 2022). "Among more than 20 MMPs, matrilysin (MMP-9) appears to be one of the most important MMPs in CRC, because it is closely related with tumor invasion and metastasis in CRC." (PMID 35574414, 2022).